STAT3 (signal transducer and activator of transcription 3)
Diseases named in the same sentence as STAT3 in open-access papers (continued):
Sharing a sentence is not in itself a finding about the gene and the disease.
gastric tumor (41 papers, 2010 to 2025). "The development and spread of cancers have been linked to aberrant STAT3 activation in gastric tumor cells." (PMID 40217305, 2025). "By exploiting the spontaneous Stat3-dependent formation of inflammation-associated gastric tumors in Gp130F/F mice, we functionally established miR-21 as a Stat3-controlled driver of tumor growth and progression." (PMID 35053428, 2022). "Another study implicated the role of STAT3 signaling in angiogenesis of gastric tumors by regulation of its target genes cyclin D1, Bcl-xL and VEGF." (PMID 29383166, 2017). "gp130757FF mice spontaneously develop antral stomach tumors caused by constitutive activation of STAT3 and by 30 weeks of age the antrum of a gp130757FF mouse is largely tumor tissue." (PMID 25528766, 2015). "Since we have previously shown that EGFR ligands are up-regulated at critical times during gastric tumour development in the gp130757FF mouse, the expression and susceptibility of 2 of these ligands to blockade of STAT3 activation were measured." (PMID 24804649, 2014). "Meanwhile, systemic reduction of Stat3 expression in gp130Y757F;Stat3+/- mice not only prevented gastric tumour formation, but also reduced their susceptibility to colonic tumourigenesis in the CAC model." (PMID 20478049, 2010). "STAT3 signaling has been linked to the development of gastric tumors in mice." (PMID 30884828, 2019). "Gastric tumors in gp130FF mice, which harbor a knock in germline mutation in the shared IL-6/IL-11 receptor subunit gp130, arise from excessive IL-6/IL-11 dependent STAT3 activity; these tumors remain associated with chronic inflammation and immune cell infiltration." (PMID 31227713, 2019). "A previous study identified the JAK2/STAT3 signal as a key driver of macrophage activation in gastric tumors." (PMID 39974738, 2025). "The identification of FOXM1 and STAT3 as top MRs in proximal gastric tumors highlights a more proliferative and inflammatory oncogenic program in PGC." (PMID 40862793, 2025). "Up-regulation of YAP1, IL11, IL6, and STAT3 mRNA transcript expression was observed in human gastric tumor samples when compared with normal gastric tissue." (PMID 37957015, 2024). "gp130F/F mice, harboring the knock-in mutation of the gp130 co-receptor, show constitutive activation of gp130/STAT3 and develop gastric tumours in the antral stomach." (PMID 35677533, 2022). "Inhibition of the JAK/STAT3 pathway in gastric tumor tissues reduces the inflammatory response, inhibits the inflammatory cytokines IL-1L, IL-6, and IL-1β, and decreases tumor volume." (PMID 34686626, 2021). "STAT3 can directly up-regulate the epithelial expression of TLR2 in gastric tumors, which is related to the low survival rate of GC patients." (PMID 32831016, 2020). "Chen Z's research indicated that DARPP‐32 can further regulate the angiogenic effect of ANGPT2 by inducing STAT3 phosphorylation in gastric tumors." (PMID 33090721, 2020). "Here, we provide evidence for IL-33 expression in gastric tumor epithelium to also be stimulated by an IL-11/Stat3 signaling cascade, which we and others have identified as an absolute requirement for effective growth of gastrointestinal tumors." (PMID 31227713, 2019). "Bazedoxifene administration reduced gastric tumor burden in gp130Y757F mice, where tumors arise exclusively through excessive gp130/STAT3 signaling in response to the IL6 family cytokine IL11." (PMID 30885958, 2019). "Analyses with human gastric tumor tissue have also shown the association of STAT3 with many clinicopathological features, including TNM staging and survival, thereby establishing it as an important prognostic marker in gastric tumors." (PMID 29383166, 2017). "We also demonstrate that the levels of miR-874 expression in resected patient gastric tumor tissues are significantly lower than in adjacent normal tissues and that they are inversely correlated with STAT3 protein levels in these tumors." (PMID 25596740, 2015).
gastric tumor (continued). "gp130757FF mice develop distal stomach tumours characterised by elevated gastric IL-11 driven STAT3 activation." (PMID 24804649, 2014). "All gastric tumor samples, which expressed p-STAT3, also expressed IL-6 with weak expression detected in adjacent normal mucosa." (PMID 24116074, 2013). "Systemic Stat3 inhibition, for instance, reduced gastric tumour burden even in gp130Y757F mice that had undergone adoptive bone marrow transfer with wild-type cells." (PMID 20478049, 2010). "Another investigation has demonstrated that silence of the expression of Stat3 suppresses the proliferation of gastric tumors, and induces cell apoptosis and cell cycle shift induction both in vivo and in vitro significantly by regulating downstream protein Cyclin-D1, Survivin, and Bcl-2." (PMID 38238515, 2024). "Moreover, CAG can inhibit the DNA-binding activity of STAT3 and prevent its activation in human gastric tumor cells." (PMID 39830038, 2024). "Moreover, we also detected this site in a separate Stat3 ChIP experiment on gastric tumor DNA of Gp130F/F mice following a single administration of the gp130-ligand IL-6." (PMID 35053428, 2022). "Targeting STAT3-mediated CD44v6 up-regulation may represent a novel, effective treatment by eradicating the stomach tumor microenvironment." (PMID 28507278, 2017). "This supported the hypothesis that SIRT1 and STAT3 functioned independently in advanced tumors as important oncogenes to maintain the malignancy of stomach tumors resulting in poor survival outcomes in patients with high expression of both SIRT1 and STAT3." (PMID 28061480, 2017). "Therefore, we studied if SIRT1 and STAT3 collaborate during gastric tumor progression." (PMID 28061480, 2017). "IL-6 can induce M2 macrophage differentiation through STAT3 activation and can enhance infiltration of CD163+CD206+ macrophages in gastric tumor tissue." (PMID 30283449, 2018). "Gastric tumor-derived TNF-α induced CD45RA−CCR7− Treg subset with similar phenotype to their status in tumors and inhibited their HLA-DR expression via activating STAT3 phosphorylation." (PMID 28817117, 2017). "The resulting Stat3-dependent feed-forward signalling loop in tumor cells not only provides a therapeutic vulnerability for gastric tumors but also appears to help shaping aspects of the immune environment." (PMID 37957015, 2024). "Sorcin induces gastric tumor cell migration and invasion; sorcin silencing downregulates the expression of cathepsin Z, matrix metalloproteinases 2 and 9 (MMP2 and MMP9), and signal transducer and activator of transcription 3 (STAT3), resulting in the suppression of cancer growth and metastasis." (PMID 32268494, 2020). "Furthermore, expression of mRNA transcripts for the bona fide STAT3‐target genes Socs3, Icam1, and Reg3a, which are both induced by IL11 in gastric tumors, were significantly decreased in tumors from bazedoxifene‐treated animals." (PMID 30885958, 2019). "Moreover, we demonstrated that gastric tumor-derived TNF-α efficiently induced CD45RA−CCR7− Treg subset and inhibited HLA-DR expression on these cells by inducing signal transducer and activator of transcription 3 (STAT3) phosphorylation." (PMID 28817117, 2017). "Since pJAK2 and p-STAT3 are blocked by WP1066 in vitro, we tested whether WP1066 would also block gastric tumour development in vivo." (PMID 24804649, 2014). "In addition, application of intraperitoneal WP1066 for 2 weeks, reduced gastric tumour volume by 50% in the gp130757FF mouse coincident with reduced JAK2 and STAT3 activation compared with vehicle-treated, littermate controls." (PMID 24804649, 2014). "In addition, mast cell numbers in gp130FF; Stat3+/− compound mutant mice, which neither develop gastric tumors nor the other pan-inflammatory changes observed in their Stat3-proficient gp130FF; Stat3+/+ littermates, remained comparable to those in wild-type mice." (PMID 31227713, 2019).
gastric tumor (continued). "As with the gastric tumor subtypes, expression of TEAD1, but not that of YAP1 or STAT3, varied across the TME subtypes." (PMID 37957015, 2024). "Bazedoxifene suppresses gastric tumor growth in gp130Y757F mice irrespective of their gender, in which tumors arise through excessive IL11‐dependent STAT3 signaling." (PMID 30885958, 2019).
multiple sclerosis (41 papers, 2010 to 2025). A progressive autoimmune disorder affecting the central nervous system resulting in demyelination. "Alleles associated with lower NDI were associated with larger WMH volume at chr5q14.3 (VCAN) and with higher pulse pressure and lower risk of multiple sclerosis (MS) at chr17q21.2 (STAT3), all at genome-wide significance." (PMID 38811690, 2024). "Here, we analyzed somatic mutations in the STAT3 SH2 domain in peripheral blood CD8+ cells in a set of 94 multiple sclerosis (MS) patients and 99 matched controls." (PMID 36441748, 2022). "Stat3 is induced by IL6 canonical signaling in CD4+ T cells and IL6/Stat3 axis signaling contributes to the development of Th17 cells and is associated with several human diseases, such as multiple sclerosis (MS) and RA." (PMID 35126382, 2021). "A very recent genome-wide association study identified STAT3 as a new susceptibility gene for multiple sclerosis (MS), a disorder in which the Th17 pathway plays a major role." (PMID 20454450, 2010). "Discovered STAT3 somatic mutations in 94 multiple sclerosis (MS) patients and 99 controls (Ctrl)." (PMID 36441748, 2022). "In addition, a circRNA derived from a multiple sclerosis (MS)-associated locus, hsa_circ_0043813 from the STAT3 gene, can be modulated by the three genotypes at the disease-associated SNP." (PMID 32614786, 2020). "JAK/Stat3 activation in astrocytes has been detected in a plethora of conditions and disease models that are associated with astrogliosis, including stroke, AD, spinal cord injury, multiple sclerosis, and epilepsy." (PMID 30617153, 2019). "When combining male and female data, a stress-related decline in hsa-miR-301a-3p emerged, predicted to control autoimmune cell differentiation through regulating STAT3 in multiple sclerosis patients." (PMID 40188313, 2025). "Although the S1P and STAT3 signaling pathways are mostly reported in cancer research, a recent preclinical study of multiple sclerosis suggests that S1PR1 in microglia promotes the activation of downstream STAT3 signaling pathways in microglia." (PMID 35144528, 2022). "We have previously shown that anatabine inhibits STAT3 and NFκB activation resulting in decreased neuroinflammation in a mouse model of multiple sclerosis." (PMID 26010758, 2015). "For example, most focus on the role of STAT3 in autoinflammatory diseases, such as uveitis and multiple sclerosis, has been on its involvement in the differentiation and expansion of pathogenic Th17 cells." (PMID 24204098, 2013). "CD4-STAT3KO mice are also resistant to experimental autoimmune encephalomyelitis (EAE), an animal model of human multiple sclerosis, further underscoring requirement of STAT3 pathway in CNS inflammatory diseases." (PMID 22238646, 2012). "Because STAT1 and STAT3 are required for the development of naïve T cells into Th1 and Th17 lymphocyte, pre-clinical studies examined whether simultaneous inhibition of STAT1 and STAT3 with SBT-100 would be effective therapy for multiple sclerosis." (PMID 40114923, 2025). "This miRNA suppresses Th17 differentiation via targeting STAT3 in multiple sclerosis." (PMID 36293192, 2022). "Peroxisome Proliferator-Activated Receptor-γ (PPAR-γ) agonists inhibit Th17 differentiation in isolated T cells derived from multiple sclerosis and healthy patients by blocking STAT3 and downregulating RORγt, with a subsequent decrease in IL-17A protein production." (PMID 32987705, 2020). "For example, inhibiting Stat3 activation in astrocytes in spinal cord injury, where strong astrogliosis contributes to scar formation, worsens outcome, but has the opposite effect in models of multiple sclerosis or neonatal hypoxic brain damage." (PMID 30617153, 2019). "In multiple sclerosis (MS), a prototypical organ-specific autoimmune disorder, downregulation of ZEB1 effectively suppresses STAT3 phosphorylation and subsequent IL-17 expression, thereby attenuating the differentiation of pathogenic Th17 cells." (PMID 40016707, 2025).
multiple sclerosis (continued). "In a multiple sclerosis mouse model, ER stress-induced activation of the JAK1–STAT3 axis led to the expression of interleukin 6 and several chemokines, and the activation of STAT3 signaling was dependent on PERK." (PMID 40384344, 2025). "p-STAT3 expression in the CD4+ and CD8+ T cells in peripheral blood is higher in patients with active multiple sclerosis than in healthy patients, besides, in several cases of recurrent sclerosis, the p-STAT3 level is closely related to T cell response function." (PMID 33435880, 2021). "Thus, in an earlier study it was reported that FTY720, an antagonist of S1PR signaling that is already approved for the treatment of patients with multiple sclerosis, can inhibit S1PR1 expression, downregulate STAT3 activity, and inhibit the growth of DLBCL cells both in vitro and in vivo." (PMID 38339325, 2024).
periodontitis (41 papers, 2015 to 2026). An acute or chronic inflammatory process that affects the tissues that surround and support the teeth. "It has been demonstrated that far less inflammatory bone loss occurs in periodontitis mice due to the suppression of the STAT3 pathway." (PMID 41050338, 2025). "Regarding Th17 polarization‐related markers, increased expression of STAT3 and RORγT has been found to be closely linked to alveolar bone loss induced by high IL‐17 expression in mice with periodontitis." (PMID 32406154, 2020). "In addition to improving our understanding of the molecular causes of periodontitis, this method enables the prioritization of transcriptional regulators essential for inflammation and bone resorption, including STAT3, RELA, and NF- κB." (PMID 41050338, 2025). "Therefore, the use of STAT3 inhibitors can interrupt the pro-inflammatory process and have an antagonistic effect on periodontitis-associated inflammation, as previously reported." (PMID 37490712, 2023). "The findings of this study suggest that iPTH might reduce alveolar bone loss during OTM in rats with periodontitis through STAT3/β-catenin crosstalk." (PMID 33380723, 2020). "Notably, targeted knockdown of LncRNA SPIRE1 or PRLR or transfection of miR-181a-5p mimics activated the JAK/STAT3 signaling in normal BM-MSCs, while treatment with STAT3 inhibitor C188-9 restored the immunomodulatory properties of periodontitis-associated BM-MSCs." (PMID 37490712, 2023). "Our data highlight the exacerbating effect of hypobaric hypoxia on neuroinflammation in periodontitis model mice, mediated through the activation of the STAT3 signaling pathway." (PMID 40799647, 2025). "In this study, exposure to hypobaric hypoxia significantly enhanced the activation of the STAT3 signaling pathway in periodontitis mice." (PMID 40799647, 2025). "This suggests that the STAT3 signaling pathway exerts a pro-inflammatory effect in the process of hypobaric hypoxia exposure exacerbating neuroinflammation in periodontitis model mice." (PMID 40799647, 2025). "Studies have shown that ligature-induced periodontitis activates the STAT3 signaling pathway leading to neuroinflammation in the brain of rats." (PMID 40799647, 2025). "In a mouse model of periodontitis, daily intraperitoneal administration of Stat3 (5 mg/kg) and Stat5 (5 mg/kg) inhibitors significantly reduced P. gingivalis-induced periodontal resorption and Zbp1 induction." (PMID 40307566, 2025). "Transcriptomic network analysis has identified transcription factors (TFs), including NF-κB (NFKB1/RELA), AP-1 (FOS/JUN), and STAT3, as master regulators in periodontitis, highlighting their recent relevance." (PMID 41050338, 2025). "The involvement of γδ T cells and IL-17A/STAT3 signaling highlights the immunomodulatory effects of periodontitis in OSCC." (PMID 40924302, 2025). "Consistent with previous findings, we found that a higher level of STAT3 signaling in BM-MSCs from periodontitis mice can induce more IL-17 production and higher expression levels of RORC in CD4 T cells." (PMID 37490712, 2023). "Our results indicate that the JAK/STAT3 pathway is involved in the immunoregulation of BM-MSCs, and provide critical insights into the development of novel targeted therapies against periodontitis." (PMID 37490712, 2023). "To validate the contribution of the activated JAK/STAT3 signaling on the impaired immune modulation ability of BM-MSCs from periodontitis mice, we additionally treated these BM-MSCs with C188-9 before and during their co-culturing with the CD4+ T cells." (PMID 37490712, 2023). "These new findings suggested that the IL-17/STAT3 pathway was regulated by γδ T cells in response to the oral microbiota from periodontitis, which were highly important to the development of tumors." (PMID 36000726, 2022). "The reciprocal action of STAT3 and FOXO1 on ITGB6 downregulation was also confirmed by the immunostaining of the inflammatory epithelium associated with periodontitis." (PMID 36299623, 2022).